MYH6 (myosin heavy chain 6)
Diseases named in the same sentence as MYH6 in open-access papers (continued):
Sharing a sentence is not in itself a finding about the gene and the disease.
Hypertension (6 papers, 2019 to 2025). The presence of chronic increased pressure in the systemic arterial system. "Our findings suggest that age- and sex-related effects on myosin gene expression in the human left ventricle are primarily driven by MYH6 transcriptional regulation, with hypertension playing a significant contributory role." (PMID 41295372, 2025). "When comparing sexes, older females with hypertension emerged as a distinct subgroup, particularly regarding MYH6 gene expression." (PMID 41295372, 2025). "Collectively, these findings indicate that the combined effects of age, sex, and hypertension are most pronounced in the subgroup of older females with hypertension, where the greatest transcriptional differences in MYH6 (and occasionally MYH7) were observed." (PMID 41295372, 2025). "DS‐induced hypertension also reduced the expression of MYH6, though the effect size was more than two fold lower than that of obesity and appeared additive, not synergistic." (PMID 31368189, 2019). "In summary, older females with hypertension and under the threshold represented 35% of all females in the higher age group with hypertension, 22.09% of the total number of females in the database and accounted for 49% of all control samples with MYH6/MYH7 ratios below the threshold." (PMID 41295372, 2025). "Importantly, the difference in MYH6 expression between older females with hypertension and both younger males and older males with hypertension remained statistically significant after correction for multiple testing." (PMID 41295372, 2025). "Statistical analysis demonstrates sex-specific differences in MYH6 and MYH7 expression in healthy left ventricles, with postmenopausal females (aged > 50 years) with hypertension emerging as a distinct group." (PMID 41295372, 2025). "Western blot showed that MYH6 protein levels were elevated in hypertension mice compared in control mice, and SIRT3‐KO up‐regulated the expression of MYH6 compared with WT group." (PMID 34180125, 2021). "In contrast to MYH7, MYH6 expression was consistently and significantly downregulated in all comparisons, regardless of age, sex, or hypertension status." (PMID 41295372, 2025). "The availability of newly generated RNA sequencing data from a substantially larger cohort has enabled us to reanalyse the expression patterns of MYH6 and MYH7 in healthy human left ventricles, considering age, sex, and the presence of hypertension as potential modifiers." (PMID 41295372, 2025). "Additionally, the comparison between older females with hypertension and younger males without hypertension was unique in that both MYH6 and MYH7 were significantly differentially expressed, even after correction for multiple testing." (PMID 41295372, 2025). "An important observation was that MYH6 expression was consistently downregulated in all DCM samples compared to healthy controls, irrespective of sex, age, or hypertension status." (PMID 41295372, 2025). "Notably, 39 healthy heart samples also displayed MYH6/MYH7 ratios below this threshold, with 19 (48%) of females of higher age with hypertension and eight older females without hypertension (21%)." (PMID 41295372, 2025).
ischemic cardiomyopathy (6 papers, 2022 to 2025). Ischemic cardiomyopathy is a cardiomyopathy in which a weakness in the muscle of the heart due to inadequate oxygen delivery to the myocardium with coronary artery disease being the most common cause. "Changes in MYH6 gene expression can lead to alterations in myocardial structure, thereby affecting ventricular remodeling, resulting in cardiac enlargement and sinus node dysfunction, which are closely associated with ischemic cardiomyopathy and HF." (PMID 40406620, 2025). "Based on the bioinformatics analysis, Myh6, Myh7, and Fn1 were selected to have pivotal roles in cardiac cell contraction and ischemic cardiomyopathy." (PMID 40271502, 2025). "Previous studies described how MYH6 defects contribute to ventricular remodeling, causing a spectrum of phenotypes comprising DCM, HCM, ischemic cardiomyopathy and HF." (PMID 36008935, 2022).
myocardial infarction (6 papers, 2021 to 2025). Gross necrosis of the myocardium, as a result of interruption of the blood supply to the area, as in coronary thrombosis. "Inhibition of Tip60 specifically in cardiomyocytes usingtamoxifen-induced Myh6-Cre recombinase three days after myocardial infarction(MI) attenuated post-infarct apoptosis, scar formation, and cardiac remodelingin mice." (PMID 39958699, 2024). "The Myh6/7 beacons used in this study have previously been used to purify human induced pluripotent stem cell(iPSC)-derived cells, which integrated into ischemic myocardium and elicited therapeutic benefits after transplantation in a mouse model of myocardial infarction." (PMID 37840130, 2023). "At the same time, in GSE60993, MYH6 expression was lower in both non‐ST‐segment elevation acute myocardial infarction (NSTEMI) and ST‐segment elevation acute myocardial infarction (STEMI) patients than in healthy controls (p < 0.05)." (PMID 34697898, 2021).
Sepsis (6 papers, 2011 to 2024). Sepsis is defined as life-threatening organ dysfunction caused by a dysregulated host response to infection. "In three spots found higher and abundant in 48 h sepsis, myosin-6 (“MYH6”) from spots ID 57 and ID 73 and myosin-7 (“MYH7”) from spot ID 71 were identified." (PMID 28246552, 2017). "MYH6 and MYH7 appear to be the only upregulated proteins during the late stage of sepsis-induced kidney injury." (PMID 28246552, 2017). "As compared to the early phase of sepsis (24 hours after CLP), MYH6 (avg." (PMID 28246552, 2017).
Ventricular arrhythmia (6 papers, 2021 to 2025). "In 24 mice models ventricular arrhythmias were reported, most frequently in models with sarcomere mutations: Tnnt2 (n = 10 [41.7%]), Myh6 (n = 4 [16.7%]), and Mybpc3 (n = 3 [12.5%])." (PMID 40306862, 2025). "The Myh6-McmTam:DspF/F mice showed severe cardiac systolic dysfunction and ventricular arrhythmias, and died prematurely with a median survival rate of ~2 months." (PMID 36818425, 2023). "In three generations of Australian family, the MYH6 p.R654T resulted in early‐onset sinus node dysfunction, ventricular arrhythmias, and subsequent cardiac arrest." (PMID 33949037, 2021). "We then developed a mouse Pak2ctg model with inducible cardiac‐specific overexpression of wild type Pak2 driven by Myh6‐creERT to explore effects of Pak2 overexpression on acute isoproterenol or TAC‐induced ventricular arrhythmias." (PMID 40068092, 2025). "No significant supraventricular or ventricular arrhythmias were recorded in the Myh6-MCM:Ctnnb1LoF and Myh6-MCM:Ctnnb1GoF mice." (PMID 35224561, 2022).
diabetes (5 papers, 2020 to 2026). "Significant differences or trends in Myh6 and Mhy7 with diabetes and genotype translated into a significant increase in the Myh7 / Myh6 ratio with diabetes in both genotypes, with a trend for a greater increase in KO mice (p = 0.14)." (PMID 38054572, 2023). "However, the Myh6 and Myh7 genes were mostly comparable between WT and KO animals with diabetes, with the Myh7/Myh6 ratio demonstrating a significant increase by ~20–30 fold in both WT and KO mice with diabetes." (PMID 38054572, 2023).
breast carcinoma (4 papers, 2014 to 2023). "Survival and Cox analyses of all the DEGs confirmed CCL1 and MYH6 were independent protective factors and IFNK and SOAT2 were independent risk factors for basal-like breast cancer (95%CI: 1.06–2.5, p = 0.026)." (PMID 36694223, 2023). "On the contrary, IFNK, MYH6, and SOAT2 have rarely been reported in association with breast cancer." (PMID 36694223, 2023). "It is reported that MYH6 and ZNF839 are associated with breast cancer." (PMID 31888641, 2019). "We further constructed a four-gene signature comprising CCL1, IFNK, MYH6, and SOAT2 genes, which shows a promising predictive value for basal-like breast cancer and may be related to the underlying Th1/Th2 balance regulation mechanism, which is worthy of further study." (PMID 36694223, 2023). "CCL1, MYH6, IFNK, and SOAT2 have an independent prognostic value of survival outcome and might be novel markers in basal-like breast cancer." (PMID 36694223, 2023). "Research on breast cancer cell lines indicates an inhibitory effect of 17β-estradiol, BPA and other known endocrine disruptor compounds; genistein and polychlorinated biphenyl congener 54 (PCB54), on the Myh6 transcript levels." (PMID 24586524, 2014).
hypothyroidism (4 papers, 2020 to 2024). Abnormally low levels of thyroid hormone. "This observed antithetical shift in expression of cardiac myosin is consistent with previous studies showing hypothyroidism induced chemically in the rat caused a similar downregulation in MYH6 (AKA α-myosin) and upregulation in HYH7 (AKA β-myosin)." (PMID 32228691, 2020). "Basic experiments have reported that hypothyroidism suppresses myosin heavy chain 6 protein expression and enhances myosin heavy chain 7 protein expression and that hypothyroidism induces cardiac atrophy as a result." (PMID 34733168, 2021).
familial dilated cardiomyopathy (3 papers, 2019 to 2023). A a genetic form of heart disease that occurs when heart (cardiac) muscle becomes thin and weakened in at least one chamber of the heart, causing the open area of the chamber to become enlarged (dilated). "Role of myosin heavy chain 6 (MYH6) gene has earlier been associated in familial dilated cardiomyopathy." (PMID 31692905, 2019).
hyperthyroidism (3 papers, 2020 to 2024). Overactivity of the thyroid gland resulting in overproduction of thyroid hormone and increased metabolic rate. "The expression levels of Mhrt, Brg1 and Myh6/Myh7 have been assessed in rat models of hyperthyroidism or acute myocardial ischemia/reperfusion (IR) treated with T3 replacement therapy." (PMID 32987653, 2020).
myocardial ischemia (3 papers, 2024 to 2025). A disorder of cardiac function caused by insufficient blood flow to the muscle tissue of the heart. "Deptor knockout mice were constructed by crossing Deptor Floxp3 mice with myh6 Cre mice, establishing a myocardial ischemia-reperfusion (I/R) model." (PMID 39702468, 2024). "To investigate the impact of SENP1 in myocardial ischemia in vivo, we generated cardiac muscle tissue‐specific SENP1 knockdown (SENP1‐TKO) mice by crossing Myh6‐MerCreMer mice with SENP1fl/fl mice." (PMID 40341856, 2025).
Obesity (3 papers, 2018 to 2024). Accumulation of substantial excess body fat. "Overall, maternal diet-induced obesity led to an increased ratio of Myh7: Myh6 (two-way ANOVA, P = 0.0005)." (PMID 29635288, 2018). "Obesity triggered a down‐regulation of MYH6 and an up‐regulation MYH7." (PMID 31368189, 2019).
ventricular septal defect (3 papers, 2021 to 2022). The presence of a defect (opening) in the septum that separates the two ventricles of the heart. "Our study for the first time identifies variants in the promoter region of the MYH6 gene in Chinese patients with isolated and sporadic ventricular septal defect." (PMID 36209093, 2022). "Nine variants were identified in the MYH6 gene promoter and two of those variants [g.4085G>C(rs1222539675) and g.4716G>A(rs377648095)] were only found in the ventricular septal defect patients." (PMID 36209093, 2022). "In 604 of the subjects (311 isolated and sporadic ventricular septal defect patients and 293 healthy controls), DNA was extracted from blood samples and MYH6 gene promoter region variants were analyzed by sequencing." (PMID 36209093, 2022).
viral myocarditis (3 papers, 2024 to 2025). Myocarditis that is caused by an infection with a viral agent. "We also identified two positively selected genes (MYH6 and DCSTAMP) specific to Chinese serow, which were involved in 'viral myocarditis' and 'Cardiac muscle contraction'." (PMID 39385836, 2024).
cardiac arrest (2 papers, 2021 to 2022). Cessation of breathing and/or cardiac function. "Specifically, we compared a composite endpoint of cardiac arrest, need for mechanical circulatory support, and heart transplant or death between 12 HLHS patients with MYH6 and 24 HLHS patients without MYH6 variants." (PMID 35621855, 2022).
cardiac conduction disease (2 papers, 2021 to 2022). "Specifically, researchers evaluated the ability of the human MYH6-E933del and MYH6-R1252Q variants, which are associated with cardiac conduction disease, to rescue cardiac impairments resulting from myh6 knockdown." (PMID 35621855, 2022).
COVID-19 (2 papers, 2022 to 2023). A disease caused by infection with severe acute respiratory syndrome coronavirus 2. "Whether the mimicry between SARS-CoV-2 Replicase polyprotein 1a/1ab and wild-type or mutant MYH6 contributes to cardiac inflammation in the setting of COVID-19 warrants further investigation." (PMID 35314694, 2022).
dilatation (2 papers, 2021 to 2023). "The Myh6-McmTam:DspF/F mice exhibited severe cardiac dilatation and dysfunction at 4 weeks of age, consistent with their high mortality rate." (PMID 36818425, 2023).
Ebstein anomaly (2 papers, 2018 to 2023). Ebstein's malformation is a rare congenital cardiac anomaly characterized by rotational displacement of the septal and inferior leaflets of the tricuspid valve such that they are hinged within the right ventricle, rather than as expected at the atrioventricular junction. "Heterozygous pathogenic variants in MHY7 have been associated with septal defects or Ebstein anomaly and of MYH6 with HLHS and cardiac conduction." (PMID 37322441, 2023).
hyperglycaemia (2 papers, 2018 to 2022). "Overexpression of (Myh6/Ghrl) in transgenic rats lessened oxidative stress and prevented fat dietary–induced hyperglycemia." (PMID 35456988, 2022).
infarction (2 papers, 2017 to 2022). A localised pathological necrosis of tissue resulting from obstruction of the blood supply usually by a thrombus, an embolus, or vascular torsion. "mRNA levels coding for troponin I (+40%) and myh6 (+60%) were increased in the ZI+BZ area of LCZ696-treated hearts 10 days after infarction, suggesting higher number of cardiomyocytes in these areas when compared to untreated infarcted hearts." (PMID 36611800, 2022). "Although MYH6 was included as a biological determinant in the HF but not infarction model (according to microarray data), this protein ultimately does not seem to participate in Sacubitril/Valsartan efficacy in HF, but may play a role in MI instead." (PMID 28649439, 2017).
myocardial diseases (2 papers, 2011 to 2022). "The expression of its encoding genes, MYH6 and MYH7, is implicated in regulatory processes governing cardiac function and is also significantly altered in various myocardial diseases." (PMID 36157891, 2022).
osteoporosis (2 papers, 2024 to 2025). A condition of reduced bone mass, with decreased cortical thickness and a decrease in the number and size of the trabeculae of cancellous bone (but normal chemical composition), resulting in increased fracture incidence. "Alleles associated with slower heart rate (rs365990, MYH6), decreased risk of osteoporosis and short body height (rs2982570, ESR1), decreased risk of schizophrenia (rs1339227, RIMS1-KCNQ5) and decreased risk of anxiety and neuroticism (rs391957, HSPA5) were found to have higher frequency in LLIs." (PMID 39567526, 2024).
arrhythmogenic right ventricular cardiomyopathy (1 paper, 2022). "MYH6 variants are also associated with all types of cardiomyopathy, including HCM, dilated cardiomyopathy (DCM), peripartum cardiomyopathy (PPCM), arrhythmogenic right ventricular cardiomyopathy (ARVC), and left ventricular non-compaction (LVNC)." (PMID 35621855, 2022).
bladder cancer (1 paper, 2021). "Importantly, MYH6 expression levels were significantly associated with age in bladder cancer, while MYBPH exhibited a negative correlation with age." (PMID 33436826, 2021).
brain tumors (1 paper, 2024). "Some of the frequently mutated genes have been rarely reported in brain tumors according to the COSMIC database: EPH2B (67% vs 1.11%), DICER1 (67 vs 1.25%), KMT2B (67% vs 1.46%), ATRX (67% vs 13.95%) as well as several muscular genes (DMD, MYO10, MYO9B, MYH6) (P < .00001, Fischer exact test)." (PMID 39233831, 2024).
familial cardiomyopathies (1 paper, 2011). "Three MYH6 mutations were novel and two (one MYH6 and one MYBPC3) were previously found in patients with familial cardiomyopathies." (PMID 22194935, 2011).
fibrosis (1 paper, 2023). the formation of excess fibrous connective tissue in an organ or tissue in a reparative or reactive process. "Consistent with previous studies in Lmna−/− and Myh6-Cre:Lmnaf/f mice, Lmnaflox/floxSM22αCre mice showed evidence of cardiac fibrosis and apoptosis, which was accompanied by elevated fibroblast and myofibroblast markers, including WGA staining and immunostaining of FSP-1 and SMA." (PMID 37446344, 2023).
Hypercholesterolemia (1 paper, 2022). An increased concentration of cholesterol in the blood. "Furthermore, hypercholesterolemia seemed to negatively affect the protein expression pattern of the ventricular isoform of myosin light chain (MYL3), as well as myosin heavy chain 6 (MYH6), which is preferably expressed in the ventricles of smaller mammals with rapid heart rates." (PMID 35806390, 2022).
idiopathic dilated cardiomyopathy (1 paper, 2025). Decreased function of the heart associated with cardiac enlargement and congestive heart failure, of unknown cause. "In patients with idiopathic dilated cardiomyopathy, MYH6 is decreased, and is increased again in patients with improved cardiac function in response to beta-blocker therapy." (PMID 40562874, 2025).
iron deficiency (1 paper, 2016). "Prevention of cardiac dysfunction in Hampfl/fl;Myh6.Cre+ mice by intravenous iron treatment confirms the causal relationship between cardiomyocyte iron deficiency and cardiac dysfunction in this setting." (PMID 27897970, 2016). "As cardiomyocyte iron deficiency preceded the development of cardiac dysfunction, we hypothesised it is the cause of the cardiac phenotype in Hampfl/fl;Myh6.Cre+ mice." (PMID 27897970, 2016).
kidney damage (1 paper, 2016). "The most linked proteins included Myh6, Myh7, Myh11, Lmna, Des, Tnni3, Mydpc3 and Vcl, revealing that these molecules may be important targets of signaling pathways involved in salt sensitivity in advanced kidney damage." (PMID 27775022, 2016).
oral cancer (1 paper, 2022).
osteosarcoma (1 paper, 2021). A usually aggressive malignant bone-forming mesenchymal neoplasm, predominantly affecting adolescents and young adults. "Among them, the expression of MYH6 and SULT4A1 in osteosarcoma was higher than that in control group, while the expression of LIPE, ACTG2, KLF4, and TF was decreased." (PMID 34104648, 2021).
Parkinson disease (1 paper, 2025). A progressive degenerative disorder of the central nervous system characterized by loss of dopamine producing neurons in the substantia nigra and the presence of Lewy bodies in the substantia nigra and locus coeruleus. "Notably, LUZP2, CLO1, and MYH6 genes were also associated with Parkinson’s disease in PheWASs." (PMID 40826483, 2025).
Patent foramen ovale (1 paper, 2016). Failure of the foramen ovale to seal postnatally, leaving a potential conduit between the left and right cardiac atria. "Mutations in the MYH6 gene (myosin heavy chain 6) have been commonly linked to the following CHD phenotypes: ASD, AS, TGA, and patent foramen ovale (PFO)." (PMID 26805889, 2016).
prostate carcinoma (1 paper, 2023). A carcinoma that arises from epithelial cells of the prostate gland. "MYH6 and SOAT2 may be associated with the progression of prostate cancer." (PMID 36694223, 2023).